TMCC2 (transmembrane and coiled-coil domain family 2)
Description:
May be involved in the regulation of the proteolytic processing of the amyloid precursor protein (APP) possibly also implicating APOE.
Synonyms: HUCEP11; FLJ38497
Tractability: Antibody: UniProt predicts a signal peptide or a membrane-spanning region. PROTAC: its protein half-life has been measured.
Gene: Protein-coding gene on chromosome 1 (205,227,912 to 205,285,632, forward strand). Ensembl gene ENSG00000133069.
Subcellular location: Endoplasmic reticulum membrane
Gene Ontology:
Molecular function: protein binding
Biological process: amyloid precursor protein metabolic process
Cellular component: endoplasmic reticulum; endoplasmic reticulum membrane; endomembrane system
Genetic constraint (gnomAD): Loss-of-function variants: 16 observed, 50.21 expected, observed/expected ratio (o/e) 0.32, 90% interval 0.22 to 0.48. The upper end of that interval is the gene's LOEUF score, 0.48, which puts it in group 2 of 6, group 1 being the genes least tolerant of losing a copy. Missense variants: 762 observed, 1,018 expected, observed/expected ratio (o/e) 0.75, 90% interval 0.7 to 0.8. Synonymous variants: 397 observed, 447.33 expected, observed/expected ratio (o/e) 0.89, 90% interval 0.82 to 0.96.
Homologues: Orthologues: chimpanzee TMCC2 (99% identical), macaque TMCC2 (99% identical), dog TMCC2 (97% identical), guinea pig TMCC2 (96% identical), mouse Tmcc2 (94% identical), rat Tmcc2 (94% identical), pig TMCC2 (86% identical), rabbit TMCC2 (83% identical), tropical clawed frog tmcc2 (74% identical), zebrafish tmcc2 (51% identical), Drosophila melanogaster Dmtn (33% identical), Caenorhabditis elegans C15H9.4 (16% identical). Paralogues in human: TMCC1 (53% identical), TMCC3 (37% identical), TEX28 (18% identical).
Diseases named in the same sentence as TMCC2 in open-access papers:
TMCC2 is named in the same sentence as 18 diseases in open-access papers, as found by Europe PMC text mining. Sharing a sentence is not in itself a finding about the gene and the disease. The quoted sentences say what the papers report.
Alzheimer disease (4 papers, 2013 to 2025). A progressive, neurodegenerative disease characterized by loss of function and death of nerve cells in several areas of the brain leading to loss of cognitive function such as memory and language. "Transmembrane and coiled‐coil 2 (TMCC2) is a human orthologue of the Drosophila gene dementin, mutant alleles of which cause neurodegeneration with features of Alzheimer's disease (AD)." (PMID 39084860, 2025). "We previously identified TMCC2 as a protein that interacted differentially with normal versus Alzheimer's disease-risk forms of both apolipoprotein E (apoE) and the amyloid protein precursor (APP)." (PMID 23409049, 2013). "Transmembrane and coiled‐coil 2 (TMCC2) is an apolipoprotein E‐binding protein with an evolutionarily conserved interaction with the amyloid protein precursor family, mutation of whose Drosophila orthologue causes neurodegeneration with features of Alzheimer's disease (AD)." (PMID 39084860, 2025). "TMCC2 is a neuronal, ER-located protein, and the interaction between TMCC2 and apoE contributes to amyloid-β protein precursor metabolism in Alzheimer’s disease." (PMID 33742122, 2021). "In view of the analogies between prion diseases and Alzheimer’s disease, the regulation of PrPC via TMCC2 may occur through a common mechanism." (PMID 34705895, 2021). "Transmembrane and coiled‐coil 2 (TMCC2) forms an evolutionarily conserved complex with the amyloid protein precursor (APP), the source of the Aβ peptide whose accumulation as amyloid plaques in the brain defines Alzheimer's disease (AD)." (PMID 39084860, 2025).
amyloid (1 paper, 2025). "To investigate whether TMCC2 associates with amyloid plaques, we stained AD cases using anti‐TMCC2 antibody 94 and anti‐Aβ (antibody 4G8)." (PMID 39084860, 2025).
anaemia (1 paper, 2010). "Tmcc2 is the homologue of human TMMCC2 which has recently been strongly associated with mean corpuscular volume (MCV, red blood cell volume), a measure of anaemia, in a genome wide association study." (PMID 20844758, 2010).
bone marrow failure (1 paper, 2022). "Hence, translating our findings to clinical practice could be accelerated by a filtered retrospective analysis of the WES/WGS data previously obtained by others, focused on the TMCC2 genetic variants in patients with various bone marrow failure conditions, especially in a cohort of CDA patients." (PMID 35563652, 2022).
breast carcinoma (1 paper, 2022). "Finally, the prognostic values of RPL36, RPL27A and TMCC2 in breast cancer were evaluated using Kaplan-Meier plotter database." (PMID 35145966, 2022). "Therefore, RPL27A and TMCC2 might be two potential inflammation-related target genes of LRRC75A-AS1/miR-2114-3p pathway in breast cancer." (PMID 35145966, 2022). "No statistical role of TMCC2 in predicting prognosis of breast cancer was observed." (PMID 35145966, 2022).
congenital dyserythropoietic anemia (1 paper, 2022). Congenital dyserythropoietic anemia (CDA) is a heterogenous group of hematological disorders of late erythropoiesis and red cell abnormalities that lead to anemia. "While several phenotypic features resemble congenital dyserythropoietic anemias (CDA) types II, III, and IV, the involvement of TMCC2 in the pathogenesis of CDA in humans remains to be determined." (PMID 35563652, 2022).
COVID-19 (1 paper, 2022). A disease caused by infection with severe acute respiratory syndrome coronavirus 2. "Our results included SNPs in the genes FBXO34, Contactin 2 (CNTN2), and Transmembrane And Coiled-Coil Domain Family 2 (TMCC2) which have been previously linked with COVID-19 severity." (PMID 36143338, 2022). "This included FBXO34, CNTN2, and TMCC2 previously linked with COVID-19 severity using association studies." (PMID 36143338, 2022). "CNTN2 and TMCC2 occur in the same genomic region that is significantly associated with risk of poor COVID-19 outcomes in individuals with high European ancestry in Brazil." (PMID 36143338, 2022).
dementia (1 paper, 2025). Loss of intellectual abilities interfering with an individual's social and occupational functions. "We found that TMCC2 associates with characteristic pathologies of AD in both early and late onset AD, and shows variation in apparent molecular weight according to brain region as well as by APOE and/or dementia status." (PMID 39084860, 2025). "Thus, the form of TMCC2 present in the human brain was found to differ according to brain region as well as according to APOE and/or dementia status." (PMID 39084860, 2025). "At the protein level, western blots of human brain extracts revealed that human brain‐derived TMCC2 exists as at least three isoforms, the relative abundance of which varied between the temporal gyrus and cerebellum and was influenced by APOE and/or dementia status." (PMID 39084860, 2025).
Down syndrome (1 paper, 2025). "We found the strongest association of TMCC2 with AD pathology in Down syndrome, where, in addition to being detected in dense‐cored plaques as in late onset AD, TMCC2 immunoreactivity was also associated with putative amyloid having a spicular or thread‐like appearance (B′)." (PMID 39084860, 2025). "Further investigations into the potential for TMCC2 to adopt a β‐pleated sheet amyloid conformation in Down syndrome, or indeed also within dense core plaques of familial and late onset AD may therefore be warranted." (PMID 39084860, 2025). "We investigated TMCC2 in three Down syndrome cases with a post‐mortem pathological diagnosis of AD." (PMID 39084860, 2025). "We examined TMCC2 immunoreactivity in late onset AD cases stratified by APOE genotype and age‐matched non‐demented controls, as well as in early onset AD cases associated with mutations in APP or Down syndrome." (PMID 39084860, 2025).
erythrocyte disorder (1 paper, 2022). A disease or disorder that involves the erythrocyte. "In our opinion, more deleterious TMCC2 mutations will eventually be identified in patients who suffer from erythrocyte disorders of unexplained etiology, including CDAs." (PMID 35563652, 2022).
osteonecrosis (1 paper, 2022). A none disease characterized by death of bone tissue due to a lack of blood supply. "In addition, TMCC2 is identified as a potential biomarker of steroid-induced osteonecrosis of the femoral head." (PMID 36225939, 2022).
Sepsis (1 paper, 2025). Sepsis is defined as life-threatening organ dysfunction caused by a dysregulated host response to infection. "In conclusion, our integrative approach identified several robust gene signatures, including TNFSF10, PLVAP, and TMCC2, as potential biomarkers of sepsis severity." (PMID 40362669, 2025). "Receiver operating characteristic (ROC) analysis demonstrated high predictive accuracy for sepsis progression, with AUC values of 0.973 (TMCC2), 0.969 (TNFSF10), and 0.897 (PLVAP)." (PMID 40362669, 2025). "Key genes like TNFSF10, TMCC2, and PLVAP genes show strong diagnostic potential, providing novel insights into sepsis pathogenesis and offering promising targets for future therapeutic interventions." (PMID 40362669, 2025). "The correlation matrix highlights strong positive relationships among key genes such as TNFSF10, EPB41, PLVAP, and TMCC2, suggesting their coordinated involvement in sepsis pathogenesis." (PMID 40362669, 2025). "Receiver operating characteristics show that key genes such as TMCC2 (AUC = 0.973), TNFSF10 (AUC = 0.969), and PLVAP (AUC = 0.897) demonstrate high predictive accuracy for sepsis progression, underscoring their potential as diagnostic biomarkers." (PMID 40362669, 2025). "Although the present study is limited by the lack of experimental validation, future work will incorporate qPCR, Western blotting, and functional assays to confirm the expression and biological roles of TNFSF10, TMCC2, and PLVAP in sepsis." (PMID 40362669, 2025). "To refine candidate selection, we implemented machine learning algorithms (random forest and SVM-RFE), which robustly identified TMCC2, TNFSF10, and CTNNA1 as key predictors of sepsis severity." (PMID 40362669, 2025).
tauopathy (1 paper, 2025). Neurodegenerative disorders involving deposition of abnormal tau protein isoforms (tau proteins) in neurons and glial cells in the brain. "In late onset AD cases stratified by APOE genotype, TMCC2 immunoreactivity was associated with dense core senile plaques and adjacent neuronal dystrophies, but not with Aβ surrounding the core, diffuse Aβ plaques or tauopathy." (PMID 39084860, 2025).
TMCC2 also shares sentences with these, for which no sentence is quoted: Cognitive impairment (1 paper); dyserythropoietic anemias (1); infection (1); Insulin resistance (1); prion disease (1).